TKFC (triokinase and FMN cyclase)
Description:
Catalyzes both the phosphorylation of dihydroxyacetone and of glyceraldehyde, and the splitting of ribonucleoside diphosphate-X compounds among which FAD is the best substrate. Represses IFIH1-mediated cellular antiviral response.
Synonyms: DAK; DKFZP586B1621; NET45; TKFCD
Tractability: PROTAC: ubiquitination databases record sites on it; its protein half-life has been measured.
Target class: Enzyme; Transferase
Gene: Protein-coding gene on chromosome 11 (61,333,210 to 61,353,295, forward strand). Ensembl gene ENSG00000149476.
Subcellular location (Human Protein Atlas): Nucleoplasm; Cytosol
Pathways (Reactome):
Disease: SARS-CoV-1 activates/modulates innate immune responses; SARS-CoV-2 activates/modulates innate and adaptive immune responses
Immune System: DDX58/IFIH1-mediated induction of interferon-alpha/beta
Metabolism: Fructose catabolism
Gene Ontology:
Molecular function: FAD-AMP lyase (cyclizing) activity; glycerone kinase activity; protein binding; triokinase activity; ATP binding
Biological process: carbohydrate metabolic process; carbohydrate phosphorylation; negative regulation of MDA-5 signaling pathway; regulation of innate immune response; glycerol catabolic process; glycerol metabolic process
Cellular component: extracellular exosome; nucleus; cytosol
Genetic constraint (gnomAD): Loss-of-function variants: 43 observed, 57.3 expected, observed/expected ratio (o/e) 0.75, 90% interval 0.59 to 0.97. The upper end of that interval is the gene's LOEUF score, 0.97, which puts it in group 4 of 6, group 1 being the genes least tolerant of losing a copy. Missense variants: 683 observed, 758.46 expected, observed/expected ratio (o/e) 0.9, 90% interval 0.85 to 0.96. Synonymous variants: 303 observed, 315.9 expected, observed/expected ratio (o/e) 0.96, 90% interval 0.87 to 1.05.
Homologues: Orthologues: chimpanzee TKFC (99% identical), rabbit TKFC (93% identical), pig TKFC (93% identical), dog TKFC (91% identical), macaque TKFC (90% identical), guinea pig TKFC (88% identical), rat Tkfc (86% identical), mouse Tkfc (85% identical), tropical clawed frog tkfc (62% identical), zebrafish tkfc (56% identical), Caenorhabditis elegans W02H5.8 (39% identical).
Diseases named in the same sentence as TKFC in open-access papers:
TKFC is named in the same sentence as 7 diseases in open-access papers, as found by Europe PMC text mining. Sharing a sentence is not in itself a finding about the gene and the disease.
TKFC shares sentences with these, for which no sentence is quoted: cardiomyopathy (1 paper); cataract (1); developmental delay (1); hypertrophic cardiomyopathy (1); liver fibrosis (1); microcytic anemia (1); Obesity (1).